NHLRC3 (NHL repeat containing 3)
Tractability: Antibody: UniProt places it where antibodies can reach, with high confidence; its Gene Ontology location is reachable by antibodies, with high confidence; UniProt predicts a signal peptide or a membrane-spanning region. PROTAC: ubiquitination databases record sites on it.
Gene: Protein-coding gene on chromosome 13 (39,038,306 to 39,050,109, forward strand). Ensembl gene ENSG00000188811.
Subcellular location: Secreted
Pathways (Reactome):
Immune System: Neutrophil degranulation
Gene Ontology:
Molecular function: ubiquitin protein ligase activity
Biological process: proteasome-mediated ubiquitin-dependent protein catabolic process; protein polyubiquitination
Cellular component: azurophil granule lumen; extracellular region
Genetic constraint (gnomAD): Loss-of-function variants: 8 observed, 12.51 expected, observed/expected ratio (o/e) 0.64, 90% interval 0.37 to 1.15. The upper end of that interval is the gene's LOEUF score, 1.15, which puts it in group 5 of 6, group 1 being the genes least tolerant of losing a copy. Missense variants: 260 observed, 261.41 expected, observed/expected ratio (o/e) 0.99, 90% interval 0.9 to 1.1. Synonymous variants: 109 observed, 98.99 expected, observed/expected ratio (o/e) 1.1, 90% interval 0.94 to 1.29.
Homologues: Orthologues: chimpanzee NHLRC3 (100% identical), macaque NHLRC3 (93% identical), guinea pig NHLRC3 (86% identical), pig NHLRC3 (86% identical), dog NHLRC3 (84% identical), mouse Nhlrc3 (84% identical), rat Nhlrc3 (83% identical), rabbit NHLRC3 (79% identical), tropical clawed frog nhlrc3 (57% identical), zebrafish NHLRC3 (50% identical).
Diseases named in the same sentence as NHLRC3 in open-access papers:
NHLRC3 is named in the same sentence as 8 diseases in open-access papers, as found by Europe PMC text mining. Sharing a sentence is not in itself a finding about the gene and the disease. The quoted sentences say what the papers report.
colon cancer (4 papers, 2022 to 2025). "NHLRC3, a member of the miR-93-5p/17-5p/NHLRC3 axis, is also implicated in the progression of colon cancer, and it has even been reported to be an independent prognostic marker for colorectal cancer and a possible target for cancer therapy." (PMID 35859893, 2022). "The mRNA expression of NHLRC3 was examined by qRT-PCR, NHLRC3 were down-expressed both in colon cells and colon cancer tissues." (PMID 35574307, 2022). "Finally, DNMBP-AS1 is an miRNA sponge that competitively binds to miR-93-5p/17-5p to promote NHLRC3 expression, thus inhibiting colon cancer progression." (PMID 36871072, 2023). "Our study suggested that DNMBP-AS1 inhibited the progression of colon cancer through the miR-93-5p/17-5p/NHLRC3 axis, which could be potential therapeutic targets for CC." (PMID 35574307, 2022). "Moreover, DNMBP-AS1 inhibited colon cancer progression through the miR-93-5p/17-5p/NHLRC3 axis." (PMID 40603870, 2025).
colorectal cancer (2 papers, 2017 to 2022). A primary or metastatic malignant neoplasm that affects the colon or rectum. "For instance, a model of seven-gene signatures (NHLRC3, ZDHHC21, PRR14L, CCBL1, PTPRB, PNPO and PPIP5K2) was applied to predict OS by dividing colorectal cancer (CRC) patients into low-risk and high-risk groups." (PMID 28827775, 2017).
gastric adenocarcinoma (1 paper, 2022). "Additionally, some recent study showed using bioinformatics analysis that NHLRC3 correlates extremely well with the prognosis of gastric adenocarcinoma, and it play an important role the development of stomach cancer." (PMID 35859893, 2022).
nephrotic syndrome (1 paper, 2024). A collection of symptoms that include severe edema, proteinuria, and hypoalbuminemia; it is indicative of renal dysfunction. "Since both A1BG and NHLRC3 are plasma proteins and an increase in A1BG levels in urine has been described in nephrotic syndrome patients, we speculate their abundance in the urine of snakebite victims may act as an early indicator of impairment in the glomerular permeability barrier." (PMID 38536893, 2024).
renal failure (1 paper, 2024). "Further, the most differentially abundant proteins found to be associated with renal failure were serotransferrin (TF), alpha-trypsin 1 (SERPINA1), alpha-1B-glycoprotein (A1BG), and NHL repeat-containing protein 3 (NHLRC3)." (PMID 38536893, 2024).
tumor (1 paper, 2022). "Initial findings indicated that RANGAP1, GOPC, NHLRC3, FZD6, and IDE were significantly correlated with stem cell indices and tumor microenvironment parameters." (PMID 35859893, 2022).
NHLRC3 also shares sentences with these, for which no sentence is quoted: cancer (1 paper); stomach cancer (1).